CD47 (CD47 molecule)
Diseases named in the same sentence as CD47 in open-access papers (continued):
Sharing a sentence is not in itself a finding about the gene and the disease.
tumor (continued). "Inhibition of tumor growth by B6H12 in these models provided evidence to support the humanization of related CD47 antibodies for treating human cancer patients, which have now entered several human clinical trials (NCT02216409, NCT02367196, NCT02096770)." (PMID 26840086, 2016). "The anti-human CD47 antibody B6H12 inhibits tumor growth in several xenograft models, presumably by preventing SIRPα engagement." (PMID 26840086, 2016). "We showed that PMA-differentiated THP-1 cells eliminated tumor cells after decreasing CD47/SIRPα interaction whereas tumor cells remained unaffected in the absence of PPRHs." (PMID 27671753, 2016). "Nowadays, therapies are developed to block the interaction of tumor cells with macrophages through CD47, thereby offering an opportunity to turn TAMs against NSCLC cells by allowing the phagocytic behavior of resident macrophages." (PMID 26941482, 2016). "Further, anti-CD47 treatment was effective in reducing tumor burden of GBM5 xenografted mice as measured by bioluminescence and resulted in a significant survival benefit." (PMID 27092773, 2016). "CD47 expression on the tumor cell lines was measured by FACS analysis and isotype-matched control antibodies." (PMID 27092773, 2016). "Last, our in vivo data show that the macrophage population in the tumor environment is dynamic and shifts toward a pro-inflammatory immune M1 dominant response after anti-CD47 treatment." (PMID 27092773, 2016). "The addition of an anti-CD47 monoclonal antibody led to enhanced tumor-cell phagocytosis by mouse and human M1 and M2 macrophages." (PMID 27092773, 2016). "In this study, we used Polypurine reverse Hoogsteen hairpins (PPRHs) as a gene silencing tool to decrease CD47 in tumor cells and SIRPα in PMA-differentiated THP-1 cells with the aim to decrease their interaction and to eliminate tumor cells." (PMID 27671753, 2016). "Two antibodies that block the interaction of CD47 on tumor cells with SIRPα on macrophages have entered Phase 1 human clinical trials (NCT02216409, NCT02367196, NCT02488811)." (PMID 26813769, 2016). "Mean tumor volume by day 36 was 285.2 ± 23.7 mm3 in the CD47-shRNA group and 714.1 ± 31.8 mm3 in the control shRNA group (P < 0.05)." (PMID 27411490, 2016). "Anti-CD47 treatment of co-cultured human M0 macrophages with these tumor cells yielded a significantly higher mean phagocytosis rate of 46.7% (difference 28.3%, p = 0.0006, paired t-test)." (PMID 27092773, 2016). "Antisense suppression of CD47 in squamous lung tumors prior to irradiation showed benefit obtaining a 71% tumor size reduction." (PMID 26941482, 2016). "This was observed using both mouse and human macrophages, however, the phagocytic response by both species after anti-CD47 treatment varied by the targeted tumor cell line and the individual macrophage batch used per experiment." (PMID 27092773, 2016). "Numerous studies over the past few years, predominantly led by Weissman and colleagues, showed that blocking CD47 using anti-CD47 monoclonal antibodies allows for increased phagocytosis of cancer cells in vitro and decreased tumor burden in vivo." (PMID 26980947, 2016). "Statistical analysis revealed that 80.4% of NSCLC specimens with high CD47 expression also exhibited strong Cdc42 staining signals, and 85.3% of the tumor samples with low CD47 expression displayed low or undetectable Cdc42 signals (X2 = 33.87, P < 0.01)." (PMID 27411490, 2016). "Our in vivo findings are the first to demonstrate that disruption of the CD47-SIRPα axis and/or Fc mediated tumor cell opsonization results in a more pro-inflammatory immune presence based on the higher M1 content within treated tumors." (PMID 27092773, 2016). "The SIRPα-CD47 interaction initially recruits PMNs to tumor sites or sites of injury but later negatively regulates these cells to end the inflammatory response." (PMID 26941482, 2016).
tumor (continued). "Given the importance of SIRPα-CD47 interaction for tumor growth, CD47 has been used as a validated target for cancer therapies." (PMID 27671753, 2016). "IHC staining revealed a strong CD47-positive staining in the membrane and cytoplasm of tumor cells, compared with that in adjacent normal lung cells, which had a weak stain or no staining." (PMID 27411490, 2016). "In this study, we analyzed NSCLC specimens and cell lines, and revealed that CD47 is expressed at a higher level than in tumor-free control samples." (PMID 27411490, 2016). "Here, we show that M1 macrophages display a larger phagocytic response towards GBM than M2 macrophages upon tumor cell opsonization and/or CD47-SIRPα disruption in vitro." (PMID 27092773, 2016). "On the other hand, the potential side effects should be addressed by careful selection of patient populations based on biomarkers such as tumor CD47 overexpression." (PMID 26941482, 2016). "CD47 expression has been detected on most PCa cells and other cancer cells from primary and xenografted patient tumor samples." (PMID 27727290, 2016). "In the context of tumor immunology, tumor cells have been shown to overexpress CD47, an anti-phagocytic signal directed to macrophages to escape from phagocytosis by interacting with Signal Regulatory Protein α SIRPα." (PMID 27671753, 2016). "Neutrophils are recruited to tumor sites through transendothelial migration involving the CD47:SIRPα recognition (signal regulatory protein alpha) creating an inflammatory environment." (PMID 26941482, 2016). "In the present work, we designed Polypurine reverse Hoogsteen hairpins, PPRHs, to silence the expression of CD47 in tumor cells and SIRPα in macrophages with the aim to eliminate tumor cells by macrophages in co-culture experiments." (PMID 27671753, 2016). "Results revealed that the expression of CD47 was significantly higher in cancer tissues than in matched adjacent non-tumor tissues." (PMID 27411490, 2016). "The knockdown of CD47 in A549 cells significantly inhibited tumor growth in vivo, leading to much smaller tumors at 36 days after A549 injection." (PMID 27411490, 2016). "The aims of this study were: to decrease the levels of CD47 in tumor cells and SIRPα level in PMA-differentiated THP-1 cells with PPRHs and ultimately to eliminate tumor cells by macrophages by diminishing the CD47/SIRPα interaction in co-culture experiments." (PMID 27671753, 2016). "Disruption of the CD47-SIRPα axis by monoclonal antibodies results in enhanced phagocytosis of both solid and hematopoietic tumor cells, including increased phagocytosis of GBM cells in vitro and significant anti-tumor activity in vivo." (PMID 27092773, 2016). "The expression of SIRPα and CD47 are varies during infection and malignancies, and they are involved in the pathogenesis of various tumor, such as melanoma, leukaemia, lung cancer." (PMID 27793032, 2016). "In this work, we explored the usage of specific PPRHs to decrease the expression of CD47 and SIRPα to stimulate the elimination of tumor cells by macrophages, which constitutes a new approach in tumor immunotherapy." (PMID 27671753, 2016). "The premise for developing therapeutic antibodies that target CD47 was that high expression of this cell surface protein protects tumor cells from host innate immune surveillance." (PMID 26840086, 2016). "Macrophages were co-cultured with tumor cells in the presence of PPRHs to silence CD47 and/or SIRPα." (PMID 27671753, 2016). "CD47 is overexpressed in many human cancers, its level positively correlates with tumor invasion and metastasis." (PMID 27411490, 2016). "In order to understand the functional significance of CD47 in NSCLC tumor development, xenograft tumors were established using A549 cells stably transfected with either CD47-shRNA or control shRNA, and followed tumor growth over time." (PMID 27411490, 2016).
tumor (continued). "The mean phagocytosis rate of human M1 macrophages toward all tumor cells increased significantly upon anti-CD47 treatment (overall increase 47%, p = 0.015, paired t-test)." (PMID 27092773, 2016). "CD47 has also been identified as a tumor marker, and its dysregulation contributes to cancer progression and evasion of antitumor immunity." (PMID 26941482, 2016). "CD47 functions as an inhibitor of phagocytosis, since its interaction with its receptor SIRPα in macrophages leads tumor cells to be recognized as self-molecules." (PMID 27671753, 2016). "When tumor cells treated with anti-CD47 antibodies, macrophages enhanced the phagocytic capability against tumor cells." (PMID 27793032, 2016). "We excluded markers that are known to be ubiquitously expressed on all nucleated cells (e.g. HLA) or on tumour cells (e.g. CD47) and focused our attention on five markers (CD57, CD59, CD81, CD164 and CD98) for further interrogation." (PMID 27590276, 2016). "CD47 is expressed on the surface of all human solid tumor cells, and binding to SIRPα blockade of CD47 signaling using targeted monoclonal antibodies enabled macrophage phagocytosis of tumor cells that were otherwise protected in vitro." (PMID 25658794, 2015). "In order to reach an optimal control of tumor progression, future directions will aim to associate innovative approaches targeting TSP-1/CD47 and TSP-1/CD36 signaling with existing anticancer treatments." (PMID 26578962, 2015). "We performed in vitro cellular and molecular biology assessments in primary CD5+ B lymphocytes obtained from a cohort of 80 CLL patients, and we assessed, in a CLL-xenograft mouse model, the in vivo capacity of the CD47 agonist peptides to reduce tumor burden." (PMID 25734483, 2015). "Specifically, overexpression of murine CD47 can profoundly enhance the metastatic potential of human tumor cells in the xenografted tumor models." (PMID 26674012, 2015). "Using multimodal and multi-scale imaging approaches from in silico to in vivo, we evidenced that this CD47-derived peptide disrupts tumor angiogenesis in several experimental models and reveals exciting anti-tumor properties." (PMID 26046793, 2015). "The loss of sphere-forming capacity and efficacy of tumour formation for CD24- MM cells can be linked to their loss of several other stemness markers, including CD47, EpCAM and OCT4, as shown for the tumour tissue." (PMID 25932953, 2015). "This is supported in twosyngeneic murine tumor models, in melanoma and squamous cell carcinoma, whereirradiation combined with antisense suppression of CD47 delayed tumor growth." (PMID 25621565, 2015). "In conclusion, we provide evidence that proper engagement of CD47 with its receptor SIRPα is crucial for successful establishment of tumor metastases." (PMID 26674012, 2015). "Indeed, blockade of PD-1 increased the expression levels of co-stimulatory molecular in mouse tumor and immune organ suggesting the condition of immune suppression was improved in the tumor microenvironment, which may be caused by decreased CD47/SIRPα signaling." (PMID 26573233, 2015). "CD47 blocking antibodies have been shown to directly induce apoptosis and to influence tumor proliferation in several malignant cell lines 22,38." (PMID 26077800, 2015). "While TSP-1:CD47 interaction is identified as a key signaling integrator of tumor progression, its contribution remains somewhat controversial as TSP-1 exhibits a pleiotropic activity within the tumor microenvironment." (PMID 26046793, 2015). "Our study is the first direct demonstration that overexpression of murine CD47 in human cancer cells can potentiate the metastatic potential of the tumor cells in the murine model." (PMID 26674012, 2015). "Recent studies have also demonstrated that the CD47-signal regulatory protein α (SIRPα) signaling system plays important roles in tumor immune surveillance through regulation of the phagocytic activity of macrophages." (PMID 26506238, 2015).
tumor (continued). "Our data suggested that CD47 and SIRPα significantly increased in tumor but this was attenuated by PD-1 blockade." (PMID 26573233, 2015). "We demonstrated that blockade of CD47 signaling also enable TAMs to attack tumor cells that they would otherwise disregard." (PMID 26093091, 2015). "CD47 signaling also regulates natural killer (NK) and DC functions that orchestrate adaptative immunity, leading to tolerogenic signals toward tumor under TSP-1 ligation." (PMID 26578962, 2015). "Velcro-CD47 already proved its ability to enhance macrophage phagocytosis of tumor cells in vitro and to target the monocyte subpopulation specifically, and its putative anticancer efficacy will be further evaluated in pre-clinical models." (PMID 26578962, 2015). "Among TSP-1 ligands, CD36 and CD47 cell-surface receptors act as key integrators of multiple signals regulating tumor growth and dissemination both positively and negatively." (PMID 26578962, 2015). "Considerable efforts have focused on developing CD47-targeting mAbs to block the CD47/SIRPα antiphagocytic pathway established between tumor cells and immune cells." (PMID 26578962, 2015). "The in vivo data obtained in the CLL-xenograft mouse model demonstrated that, by inducing PLCγ1-mediated, caspase-independent PCD, the injection of CD47 agonist peptides significantly reduced tumor burden." (PMID 25734483, 2015). "Sixteen mice (80%) developed tumor in IgG-treated mice and 15 mice (75%) in the anti-CD47 Abs (B6H12)-treated group." (PMID 26093091, 2015). "Selective inhibition of the CD47-SIRPα interaction on tumour cells is potentially achievable using a BiAb having one arm targeting a tumour-associated antigen and the other arm targeting CD47." (PMID 25672245, 2015). "This study was partly prompted by the recent demonstration that CD47 is a key “don’t eat me” signal, as masking CD47 on tumor cells with monoclonal antibodies allow macrophages to efficiently clear the malignant cells." (PMID 26674012, 2015). "For example, a new cancer drug that suppresses the emission of CD47 by the tumor tissues, which helps the tumor cells evade attack by the immune system, has been discovered." (PMID 25329892, 2014). "PD-1/PD-L1 interactions and CD47–SIRP-α interactions are thought to be critical immunosuppressive function in the tumor environment." (PMID 24600454, 2014). "As has been found by other investigators, CD47 over expression may be associated with ferric nitrilotriacetate-induced renal cortical tubular damage and regeneration that lead to a polycystic state, and with tumor progression and metastasis of the induced RCCs." (PMID 23943374, 2014). "CD47 expression has previously been reported to prevent tumor cell phagocytosis by the cells of the innate immune system." (PMID 25230070, 2014). "Tumor cells expressing high levels of CD47 have the ability to escape the innate immune system and therefore survive better than CD47 negative cells in the blood of patients." (PMID 25230070, 2014). "In fact, mouse tumor models that added a CD47-blocking antibody to the therapeutic regimen saw a marked improvement in tumor eradication, further supporting the importance of proper DC function in the generation of tumor immunity." (PMID 23606870, 2013). "CD47 overexpression by human solid tumor cells represents another mechanism of tumor escape by preventing tumor cells to be phagocytosed and eliminated." (PMID 24339825, 2013). "Depletion of macrophages in recipient mice allows for engraftment of CD47-low clones, and macrophage phagocytosis of AML cells both in vitro and in vivo is selective for tumor cells expressing low amounts of CD47." (PMID 23401787, 2013). "In contrast to CRT, cell surface CD47 (a DC “don't eat me” signal) is widely expressed in solid and hematogenous tumor cells." (PMID 22891162, 2012). "Indeed, blockade of the CD47–SIRPα axis is being pursued in oncology to unleash macrophage-mediated clearance of tumor cells." (PMID 41233145, 2026).
tumor (continued). "Furthermore, SIRPα on macrophage establishes a direct contact with the CD47/αvβ3‐ECD complex on tumor cells, with an angle of ≈80°–90°." (PMID 41168993, 2026). "Importantly, combinatorial blockade of IGFBP2 and CD47 synergistically suppressed tumor growth and prolonged survival in orthotopic GBM models." (PMID 41620401, 2026). "We found that targeting CD47, a macrophage checkpoint molecule, leads to anti-tumor activity via the induction of tumor cell phagocytosis and non-apoptotic cell death, providing an alternative therapeutic approach to adaptive immune checkpoint blockade strategies such as PD-1 and CTLA-4 inhibitors." (PMID 41484790, 2026). "Since αv knockdown caused a more pronounced reduction in CD47 when compared to β3 knockdown, we implanted MDA‐MB‐231 shNC or MDA‐MB‐231 shαv tumors in the mammary fat pad of nude mice and evaluated tumor growth on day 33 postimplantation." (PMID 41168993, 2026). "Furthermore, combining this nanoinducer with a CD47 monoclonal antibody markedly enhanced anti-tumor immunity through M1 macrophage-mediated tumor killing and TME remodeling." (PMID 41806329, 2026). "Although αvβ3 and CD47 coexist in most tumor cells and reinforce immune escape from macrophages, the interactions between macrophages and T cells may differ among cancer types." (PMID 41168993, 2026). "Although these studies highlight the prominent role of the CD47-SIRPα pathway in inhibiting tumor cell phagocytosis and promoting tumor immune evasion, the specific role and immunoregulatory mechanisms of the CD47-SIRPα pathway in ESCC remain poorly understood." (PMID 40926176, 2026). "Moreover, CD47 blockade in effector T cells increases granzyme B expression, further augmenting Cytotoxic T lymphocytes mediated tumor killing." (PMID 40926176, 2026). "Given the established role of the CD47–SIRPα axis in enabling tumor immune evasion by suppressing macrophage phagocytosis, we next investigated whether DNAJC13 influences macrophage infiltration in human cancers." (PMID 41601654, 2026). "Although αvβ3 on tumor cell membranes can switch between activated and inactivated states, the mechanism by which αvβ3 interacts with CD47 and stabilizes the CD47–SIRPα axis appears to rely more on its bent closed conformation or extended closed intermediate conformers." (PMID 41168993, 2026). "Is αvβ3 in an activated or inactivated state when interacting with CD47 on tumor cells?" (PMID 41168993, 2026). "Together, these findings suggest that the CD47-SIRPα axis may play a multifaceted role in the modulation of the tumor immune microenvironment in ESCC." (PMID 40926176, 2026). "Finally, our study extensively examines the functional interplay between CD47/αvβ3 heteromeric complexes at the tumor cell membrane and the CD47–SIRPα immune checkpoint." (PMID 41168993, 2026). "Specifically, blockade of the CD47 axis destabilizes processes fundamental to Treg motility, metabolic homeostasis, and persistence, thereby undermining their capacity to accumulate within the tumor niche." (PMID 41402667, 2025). "CD47 is often upregulated on tumor cells as a means of survival and immune evasion." (PMID 41322194, 2025). "Interestingly, blocking CD47 with monoclonal antibodies inhibited tumor growth and effectively eliminated CSCs through both SIRP-dependent and SIRP-independent mechanisms." (PMID 41233805, 2025). "The observed heterogeneity in multivariate analyses suggests that factors such as tumor type, geographic location, and detection methods for CD47 may exert an influence on the outcomes." (PMID 40765033, 2025). "In pre-clinical studies, blockade of the CD47-SIRPα alone results in minimal anti-tumor effects." (PMID 40408355, 2025).